SPARC (secreted protein acidic and cysteine rich)
Diseases named in the same sentence as SPARC in open-access papers (continued):
Sharing a sentence is not in itself a finding about the gene and the disease.
tumor (continued). "Attenuating effect of SPARC on tumor growth was attributed to its direct cytostatic effect on tumor cells, as well as induction of tumor cell apoptosis and its regulatory effect on tumor ECM deposition." (PMID 27105498, 2016). "Its expression is altered in cancer, but its effects on tumor growth are still poorly understood because SPARC seems to restrict, as well as to promote, tumor growth and metastasis." (PMID 27803395, 2016). "This laboratory previously analyzed the expression of SPARC in the parental UROtsa cells, their arsenite (As+3) and cadmium (Cd+2)-transformed cell lines, and tumor transplants generated from the transformed cells." (PMID 26783756, 2016). "Serial passage of the tumor transplants would be necessary to determine if the focal expression of SPARC is an overall feature of these tumors or an element lost upon serial passage." (PMID 26783756, 2016). "Tumor transplants were generated from the SPARC-transfected As+3-and Cd+2-transformed lines and their counterparts transfected with the expression vector without the SPARC ORF." (PMID 26783756, 2016). "An identical determination was performed for the As+3-and Cd+2- transformed UROtsa cell lines transfected with SPARC and each were able to form a subcutaneous tumor when transplanted into immune compromised mice (illustrated for As#3 and Cd#4)." (PMID 26783756, 2016). "Consistent with previous studies, we found that stroma-derived SPARC suppressed angiogenesis and tumor growth." (PMID 27776337, 2016). "It was demonstrated that SPARC expression was down-regulated to background levels in Cd+2-and As+3-transformed UROtsa cells and tumor transplants compared to parental cells." (PMID 26783756, 2016). "SPARC normalizes the tumor microenvironment (TME) through anti-inflammatory properties and regulation of integrin-growth factor receptor interactions or through a regulation of MMPs release." (PMID 27564266, 2016). "Differences in SPARC expression over time were also assessed for patients who had multiple tumor specimens available." (PMID 27544129, 2016). "The lysate prepared from the tumor generated from the Cd#4 cell line transfected with SPARC did demonstrate a faint band representative of the SPARC protein." (PMID 26783756, 2016). "Compared to in the tumor cells, where expression of SPARC is commonly downregulated by promoter methylation, overexpression of SPARC is frequently found in the stroma." (PMID 26731428, 2016). "The ‘albumin’ in nab-paclitaxel interacts with secreted protein acidic and rich in cysteine (SPARC), a matrix glycoprotein that has a role in tumor invasion and facilitates the uptake of paclitaxel by the tumor cells." (PMID 25935754, 2015). "The role of SPARC in tumorigenesis is controversial, and some investigations report a positive relationship between elevated levels of SPARC and more aggressive cancers, with poorer clinical outcome, even if this largely depends on the tumour type." (PMID 26703564, 2015). "Nab-paclitaxel is albumin-bound paclitaxel that increases tumor accumulation of paclitaxel through binding of albumin to the stroma rich in overexpression of SPARC." (PMID 25935754, 2015). "In the tumor interstitial space, albumin-paclitaxel complexes bind to the Secreted Protein Acidic and Rich in Cysteine (SPARC), which is overexpressed in a majority of tumors, to achieve enhanced drug targeting and penetration in tumors." (PMID 26182353, 2015). "Our immunohistochemical studies showed that SPARC expression was detected mainly in GC cells and slightly in the desmoplastic stroma surrounding tumor cells, normal epithelial cells, and stromal cells." (PMID 25859409, 2015). "The observations described here indicate that SPARC can also participate in paracrine interactions between tumor cell subpopulations and influence their metastatic potential." (PMID 25331979, 2014). "SPARC is a potential tumor-suppressor gene in 5q- syndrome, and is thought to have anti-adhesive effects, thereby promoting apoptosis." (PMID 24535175, 2014).
tumor (continued). "Remarkably, administration of doxycycline, which suppresses SPARC expression in S.sh3399 cells, significantly inhibited the tumor-stimulating effect of S.sh3399 cells on M cells." (PMID 25331979, 2014). "It has been postulated that the ability of SPARC to bind albumin in the tumor interstitium enhances the accumulation of albumin-bound drugs within the tumor space." (PMID 25161624, 2014). "It has also been proposed that albumin carriers take advantage of the presence of albondin on the endothelium and SPARC in the tumor interstitium to increase the accumulation of drugs in the tumor space." (PMID 25161624, 2014). "Being albumin-bound, nab-paclitaxel uses the gp60 and caveolae-mediated albumin transport pathway to traverse the endothelial lining of blood vessels entering the tumor interstitium where it is trapped by SPARC." (PMID 25202467, 2014). "SPARC, also termed osteonectin or BM-40, is a Ca2+-binding matricellular glycoprotein involved in wound healing, neoplasia and the mediation of cell-matrix interactions." (PMID 25013460, 2014). "In 5q- syndrome, elevated SPARC expression inhibits the growth of tumor cells, while its low expression leads to tumor development." (PMID 24535175, 2014). "Nab-paclitaxel was thought to be a good therapeutic option given the presence of SPARC overexpression which increases the concentration of paclitaxel in the tumor interstitium leading to selective tumor cell apoptosis." (PMID 25202467, 2014). "Stromal protein and mRNA expression of secreted protein, acidic and rich in cysteine (SPARC; a.k.a osteonectin), a matricellular protein involved in angiogenesis and tumor invasion, was higher in OC compared to normal ovaries and borderline tumors." (PMID 24860785, 2014). "Our findings expand the previously known functions of SPARC in tumor-stromal interactions to include interactions among neoplastic subpopulations that impinge upon the metastatic behavior of tumor cells." (PMID 25331979, 2014). "In some tumor types (e.g., breast, melanoma, and glioblastoma), SPARC expression levels correlate with more aggressive behavior, while the opposite is true in other types (e.g., ovarian, colorectal, and pancreatic)." (PMID 24484617, 2014). "In melanoma cells, high level of SPARC expression induces epithelial-mesenchymal transition and increases invasion and tumor progression." (PMID 23935929, 2013). "The analysis of the positivity of SPARC in the stroma adjacent to the tumor revealed that 59% cases showed a moderate positivity and 36% high positivity." (PMID 24396828, 2013). "In particular CASP2, JNK2, PDCD10, and ST13 have been associated with mitochondrial permeabilization and with the induction of the apoptotic process, while SPARC overexpression seems to play a tumor suppressor function in some low expressing SPARC AMLs." (PMID 24148231, 2013). "Secreted protein acidic and rich in cysteine (SPARC) regulates tumor cell-matrix interactions, and promotes cancer cell migration and metastasis." (PMID 23717325, 2013). "The statistical analysis showed a trend of correlation between high expression of SPARC in the tumor and high expression of SPARC in the stroma adjacent to the tumor (P = 0.082)." (PMID 24396828, 2013). "Our in vivo studies resulted in a significant reduction in tumor burden in animals treated with MSA along with reduced levels of SPARC in the tumor tissue." (PMID 23470450, 2013). "Albondin receptor on the endothelial cells of tumor vassels allows transcytosis of albumin across continuous endothelium while overexpressed SPARC results in accumulation of albumin within the tumor interstitium." (PMID 23344060, 2013). "In some types of cancer, SPARC correlates with poor prognosis (melanoma, glioma, prostate and breast cancer), while in others the protein functions as a tumor suppressor (ovarian and colorectal cancers)." (PMID 23383963, 2013).
tumor (continued). "On the other hand, in neuroblastoma and breast, pancreatic, lung and ovarian cancers, SPARC functions as a tumor suppressor." (PMID 23935929, 2013). "The percentage of IHC tumor and stromal SPARC expression seemed to be directly related to each other (P < 0.05)." (PMID 24396828, 2013). "The expression of SPARC on the superficial margin of the tumor showed that 17% of the cases had a moderate positivity, 14% high positivity and 59% were negative." (PMID 24396828, 2013). "This was running in line with prior reports suggesting that SPARC improves intra-tumor concentration of paclitaxel when an albumin-bound preparation is used given the high affinity of SPARC to albumin." (PMID 23638089, 2013). "Even though the comprehensive role of SPARC-mediated tumor regression is not completely understood, previous studies have clarified the anti-proliferative and counter adhesive properties of SPARC through specific cytokines and growth factors." (PMID 23123816, 2013). "The study of SPARC in hematopoietic malignancies led to conflicting reports about its role as a tumor suppressor or promoter." (PMID 23383963, 2013). "Immunochemical analysis of tumor lysates showed that SPARC levels in tumors from treated animals were lower than that in controls, although the trend did not quite reach statistical significance." (PMID 23470450, 2013). "This study confirmed the invasion-promoting role of exogenous SPARC in pancreatic cancer cells, suggesting a tumor-promoting role of ECM proteins." (PMID 24273517, 2013). "SPARC plays important roles in development, wound healing, bone formation, adipogenesis, angiogenesis, cataractogenesis, and tumor invasion or metastasis." (PMID 23349702, 2013). "SPARC in tumor tissues can alter the function of stroma and tumor cells and activate downstream pathways, such as ILK, FAK, and MAPK, especially the expression of relevant factors of angiogenesis, thereby controlling tumor growth and invasion." (PMID 24349832, 2013). "Although the role of SPARC is becoming increasingly evident in a variety of malignancies, there are conflicting informations about its contribution to tumor development and progression." (PMID 24396828, 2013). "In statistical elaboration, in which we proposed a single parameter that combined stromal and tumor expression, the expression of SPARC showed a significant correlation with histopathological grading (P = 0.011)." (PMID 24396828, 2013). "The analysis of the positivity of SPARC in the stroma adjacent to the deep side of the tumor revealed that 36% of the cases showed moderate positivity and 35.5% high positivity, whereas 18% were immunonegative." (PMID 24396828, 2013). "There also seemed to be a significant statistical correlation between the expression of SPARC in the tumor and the overall survival (P = 0.034)." (PMID 24396828, 2013). "The analysis of the positivity of SPARC in the stroma adjacent to the superficial side of the tumor showed that 26% of the cases were moderately positive, 45% highly positive, and 18.5% showed a low positivity." (PMID 24396828, 2013). "Another report described that the expression of Secreted protein acidic and rich in cysteine (SPARC) in the tumor stroma was inversely correlated with patients' survival." (PMID 24273517, 2013). "This possible approach is supported by experiments on xenograft tumor models where intraperitoneal or subcutaneous injections of SPARC inhibited tumor growth." (PMID 23383963, 2013). "High SPARC expression was observed with low histological grade, small tumor size, and high ER expression, which are all features of slowly proliferating tumors." (PMID 23638089, 2013). "The role of SPARC in tumor pathogenesis and progression seems to depend on its different functions in the tumor microenvironment." (PMID 23383963, 2013). "The objective of this study was to investigate the role of SPARC in the process of trophoblast invasion which shares many similarities with tumor cell invasion." (PMID 23935929, 2013).
tumor (continued). "SPARC overexpression also led to a significant decline in microvessel density, delayed tumor formation, and reduction of tumor size in hepatocellular carcinoma xenografts." (PMID 22481923, 2012). "SPARC can breakdown cell-cell connections to improve tumor invasion by changing E-cadherin expression." (PMID 22879971, 2012). "These phenomena suggest that SPARC plays different roles in cancer progression in different tumor cell types and acts via different signal transduction pathways." (PMID 22321704, 2012). "To assess the significance of TGFβ on the outcome of tumor progression, we performed a survival study in which tumor-bearing SPARC−/− and SPARC+/+ animals were treated with losartan." (PMID 22348081, 2012). "Previous reports have shown that SPARC is involved in tumor development, and in this study we also observed the upregulation of SPARC expression in ccRCC, suggesting the important role of SPARC in ccRCC." (PMID 22545051, 2012). "It is likely that the diverse effects of SPARC on tumor invasiveness are elicited by its ability to control the pleiotropic interactions and functions of integrins." (PMID 22481923, 2012). "Over-expression of SPARC was frequently observed in the tumor specimens analyzed, and showed statistically significant association with high tumor metastasis and poor prognosis." (PMID 22321704, 2012). "SPARC overexpression significantly reduced the size of xenografted tumour with reduced MVD, down-regulation of SPARC by RNA interference promoted the growth of xenografted tumour with increased MVD." (PMID 22957090, 2012). "We now report that losartan decreased invasion and metastasis, abrogated vasodilation, restricted permeability and regulated immune tolerance in tumor-bearing SPARC−/− mice, which effectively restored median survival to that of SPARC+/+ mice." (PMID 22348081, 2012). "SPARC is widely expressed in cancer and is thought to promote tumor progression through regulation of cell survival, invasiveness and tumor-host interactions." (PMID 22911700, 2012). "AKT inhibitor IV did further sensitize the cells to TMZ, and 0.25 μM AKT inhibitor IV in combination with 80 μM TMZ was able to suppress the survival of SPARC-expressing tumor cells to that observed for control cells treated with TMZ alone." (PMID 22480225, 2012). "We validated and quantified this result with fluorescence immunohistochemistry and found that decorin deposition in tumors grown in SPARC−/− mice was significantly reduced, not only within tumors, but at the tumor capsule (p = 0.0051)." (PMID 22348081, 2012). "Previous studies indicated that SPARC contributed to the regulation of tumour formation, although its role seemed to be cell-type specific." (PMID 22957090, 2012). "As previously reported, SPARC−/− mice succumbed to tumor burden more rapidly than their SPARC+/+ counterparts with a median survival of 28.0 days compared to 35.5 days (p = 0.0184)." (PMID 22348081, 2012). "We also found that overexpression of SPARC inhibited tumour cell-induced capillary formation of HUVECs in vitro and angiogenesis in dorsal window assay in vivo." (PMID 22957090, 2012). "An immunohistochemistry study showed that SPARC mainly expressed in stromal cells surrounding the tumour." (PMID 22957090, 2012). "The results of H&E staining showed that the tumor xenografts formed by SPARC shRNA infected cells consisted of more connective tissues and less tumor tissues." (PMID 23050783, 2012). "Actually, SPARC function in the tumour microenvironment is deeply influenced by its cellular source." (PMID 22400028, 2012). "In summary, SPARC plays a crucial role in the process of tumor invasion and metastasis in certain malignancies." (PMID 22321704, 2012). "As result, SPARC would be advantageous when suppressing tumor cell survival with HSP27 or pAKT inhibition." (PMID 22480225, 2012).
tumor (continued). "SPARC, a matricellular protein with tumor suppressor properties in certain human cancers, was initially identified in a genome-wide analysis of differentially expressed genes in chemotherapy resistance." (PMID 22069448, 2011). "SPARC has also been implicated in colonic polyp development and CRC tumour progression through the regulation of cycloxygenase-2 (COX-2) and transforming growth factor beta-1 (TGFβ-1)." (PMID 21818290, 2011). "This correlation is a result of SPARC's ability to down-regulate macrophage recruitment to the tumour site and the production and activity of interleukin (IL)-6, prostanoids and matrix metalloproteinases to decrease the associated inflammation." (PMID 21818290, 2011). "In neoplastic tissues, SPARC is expressed in the stroma and in malignant cells of some types, and affects tumor development, metastasis, angiogenesis and inflammation." (PMID 24213109, 2011). "SPARC has also been shown to have a role in growth rate modulation as demonstrated by SPARC knockout mice having increased rate of tumor growth than those mice with intact SPARC." (PMID 22016635, 2011). "Our findings are consistent with the observation that reduced SPARC levels in primary CRC xenografts can increase tumour resistance to radiation and chemotherapeutic agents." (PMID 21818290, 2011). "Aberrant SPARC expression was found in a wide variety of human cancers, contributes to tumor development." (PMID 20525171, 2010). "SPARC is an important regulator of cell growth and malignancy with complex biological effects that are cell- and tumor-type specific." (PMID 20687958, 2010). "Immunohistochemical analysis of SPARC protein expression of tumours over-expressing FGFR1-IIIb revealed that SPARC protein was up-regulated in FGFR1-IIIb over-expressing tumours." (PMID 19920824, 2010). "Previous studies have indicated that SPARC contributes to the regulation of tumour formation, although its role seems to be cell-type specific." (PMID 20087345, 2010). "For example, SPARC expression appears in several tumor microarray analyses, but was identified in the stromal compartment in our studies and in other tumor types." (PMID 20426842, 2010). "Due to potent anti-angiogenic activity in vitro, a dose of 10 mg/kg was administered 5 days a week to investigate the effects of SPARC peptides on tumor progression in the preclinical model." (PMID 20525313, 2010). "The ECM protein SPARC is a multifunctional matricellular glycoprotein that has been evaluated in various cancers but its role as either a tumor promoter or inhibitor has been controversial." (PMID 20671917, 2010). "Analysis of tumours formed with SPARC-overexpressing clones showed that SPARC overexpression reduces vessel density as determined by CD31 or factor-VIII staining." (PMID 20087345, 2010). "Previous studies indicate that purified SPARC blocked endothelial cell migration in a dose-dependent manner in PNET tumours." (PMID 20087345, 2010). "Differential expression of SPARC has been observed in various human cancers, and it is unclear why it has variable effects on tumor growth in different tissues." (PMID 20565704, 2010). "Although the anti-tumor and anti-angiogenic effects of peptide FSEN were less potent, both SPARC peptides had profound effects on the architecture of tumor-induced blood vessels." (PMID 20525313, 2010). "Recent studies demonstrate that overexpression of SPARC led to a significant decline in microvessel density, resulting in delayed tumour formation and reduction in tumour size in hepatocellular carcinoma xenografts." (PMID 20087345, 2010). "As a secreted acidic and cysteine-enriched protein in the ECM, SPARC inhibits the proliferation of different cell types and modulates tumor cell aggressive features." (PMID 20565704, 2010). "Recent studies, both in vitro and in vivo, have found the role of exogenous SPARC on tumor cell biological behaviors." (PMID 20565704, 2010).